LGALS3 (galectin 3)
Diseases named in the same sentence as LGALS3 in open-access papers (continued):
Sharing a sentence is not in itself a finding about the gene and the disease.
Myocardial fibrosis (continued). "In conclusion, our results demonstrated that galectin-3 was up-regulated in the early phase of viral myocarditis and followed by myocardial fibrosis." (PMID 30673749, 2019). "The increasing of serum level of galectin-3 was similar to the number of galectin-3 positive cells and the myocardial fibrosis." (PMID 30673749, 2019). "Galectin-3 was up-regulated in degenerated fibrotic lesions of cardiac tissues 96 hours after viral inoculation and were followed by myocardial fibrosis." (PMID 30673749, 2019). "In the incident HD group, we examined the relationship between these variables and an emerging blood biomarker, galectin-3, which is potentially a surrogate of myocardial fibrosis." (PMID 27503805, 2016). "In conclusion, we found a significant correlation between plasma and tissue Galectin-3 levels and the degree of diastolic dysfunction and severity of myocardial fibrosis." (PMID 26582585, 2015). "Plasma Galectin-3 levels progressively increased concurrently with the ECV in the DHF groups (r = 0.59, p = 0.002), indicating good correlation between plasma Galectin-3 levels and the severity of myocardial fibrosis." (PMID 26582585, 2015). "Galectin-3 is a biomarker representing an integrated pathophysiologic signal for myocardial fibrosis and ventricular dysfunction." (PMID 26368980, 2015). "Galectin-3 is one of the most important mediators between macrophage activation and myocardial fibrosis." (PMID 25180794, 2014). "Plasma galectin-3 is a biological factor produced by activated macrophages, which has the effect of promoting fibrosis and plays a certain role in the occurrence and development of heart failure, myocardial fibrosis and cardiac remodeling." (PMID 39139162, 2024). "Galectin-3 (Gal-3) is a member of the lectin family and is involved in a wide range of inflammatory, autoimmune diseases, acute cardiovascular events, atrial fibrillation (AF) and myocardial fibrosis." (PMID 37958244, 2023). "Galectin-3 (Gal-3) is another biomarker reflective of myocardial fibrosis and remodeling." (PMID 37373664, 2023). "Meanwhile, Galectin-3 might be used as an early biomarker to monitor myocardial fibrosis, being more accessible than plasma miRNAs." (PMID 37297827, 2023). "Galectin-3 (Gal-3) participates in myocardial fibrosis (MF) in a variety of ways." (PMID 36986588, 2023). "This study evaluated cardiac fibrosis in children with sickle cell disease using cardiac MRI and also aimed to detect the effectiveness of tissue Doppler echocardiography and serum galectin-3 in identifying subclinical cardiac abnormalities indicative of myocardial fibrosis." (PMID 37715793, 2023). "Furthermore, both ST2 and Galectin-3 are involved in pathophysiologic processes of heart disease in humans and are categorized as markers of myocardial fibrosis and cardiac remodeling." (PMID 35780161, 2022). "On the other hand, the unsatisfactory results of galectin-3 as a biomarker for cancer-therapy-related cardiotoxicity in humans may be related to the inability of echocardiography to accurately assess myocardial fibrosis." (PMID 36551214, 2022). "An in vitro cell experiment showed increased secretion of galectin-3 after stretching cardiac muscle cells, Galectin-3 can increase infiltration of macrophages and mast cells in myocardial cells, leading to myocardial fibrosis, myocardial stiffness and left ventricular dysfunction." (PMID 35141299, 2021). "More data are needed to confirm our findings, but it seems that galectin-3 serial testing might be a useful approach in screening for myocardial fibrosis in asymptomatic SSc patients." (PMID 34830647, 2021). "The learning of the role of galectin-3 in the processes of myocardial fibrosis, inflammation and postinfarction dysfunction has also started studies, the aim of which was the search, at molecular level, for post-transcriptional mechanisms regulating LGALS3 gene expression." (PMID 35053194, 2021).
Myocardial fibrosis (continued). "Galectin-3 (Gal-3) is currently recognized as a promising biomarker for myocardial fibrosis." (PMID 33934700, 2021). "In animal studies, serum galectin-3 level was significantly increased in animal models with volume and (or) stress overload, artificially increasing the level of galectin-3 in animals can promote the occurrence of myocardial fibrosis." (PMID 35141299, 2021). "However, in some patients, CMR detected progression of sub-clinical myocardial fibrosis that significantly correlated with elevated galectin-3 levels." (PMID 34830647, 2021). "The diagnostic value of galectin-3, a biomarker of myocardial fibrosis and inflammation, has not been extensively studied." (PMID 34573919, 2021). "Moreover, both the degree of myocardial fibrosis and serum galectin-3 concentration returned to normal after adrenalectomy." (PMID 35053194, 2021). "Galectin-3 is a biomarker of ventricular remodelling and myocardial fibrosis." (PMID 35053194, 2021). "However, the downstream pathophysiological events of galectin-3, including myocardial fibrosis, inflammation, and oxidative stress, have all been implicated in the development of AS." (PMID 32893848, 2020). "Based on this, the purpose of this study was to establish the level of galectin-3 in serum and assess its relationship with procollagens and the severity of the myocardial fibrosis in patients with MS to determine the possible role of these factors in the occurrence of AF." (PMID 32784491, 2020). "The galectin-3 positive cell numbers correlated positively with the degree of myocardial fibrosis (confirmed by Azan staining), and, importantly, the number of galectin-3-positive infiltrating cells and the degree of myocardial fibrosis were correlated with the level of serum galectin-3." (PMID 30673749, 2019). "Galectin-3 positive cell numbers were positively correlated with the degree of myocardial fibrosis." (PMID 30673749, 2019). "Galectin-3 is an established biomarker of myocardial fibrosis." (PMID 27503805, 2016). "Further, the findings imply that galectin-3 may play an important role in the regulation of myocardial fibrosis and pathogenesis of HF." (PMID 25180794, 2014). "Given the evolving role of galectin-3 and pentraxin-3 in cardiovascular pathophysiology—especially their associations with myocardial fibrosis, vascular inflammation, and prognosis in CAD—the lack of serial measurements represents a missed opportunity for a more nuanced analysis." (PMID 40430046, 2025). "Subclinical myocardial fibrosis might be monitored by Galectin-3." (PMID 37297827, 2023). "In experimental studies, rats with induced myocardial infarction had reduced myocardial fibrosis after administration of angiotensin-converting enzyme inhibitors and spironolactone, indicating that circulating galectin-3 levels could be influenced by the type of medical treatment administrated." (PMID 34722704, 2021). "Thus, the association of galectin-3 with the development of myocardial fibrosis and the risk of AF development is not in doubt, especially in patients with MS." (PMID 32784491, 2020). "We also provided evidence for the possibility that the myocardium could secret galectin-3 under the stimulation of myocardial stretching (or pressure overload), and that the secreted galectin-3 may in turn trigger myocardial fibrosis, resulting in LV diastolic dysfunction." (PMID 30413105, 2018). "Growth factors and pro-inflammatory cytokines involved in myocardial fibrosis include connective tissue growth factor (CTGF), tissue growth factor-β (TGF-β), tumour necrosis factor-α (TNF-α), interleukin-11 (IL-11) and galectin-3 (Gal-3)." (PMID 40910148, 2025). "Histological analyses further revealed reduced interstitial fibrosis and lower expression of fibrotic markers, including COL-1, COL-3, Galectin-3 and α-SMA, indicating that β-SITO mitigates myocardial fibrosis." (PMID 41567640, 2025).
Myocardial fibrosis (continued). "Conversely, galectin-3 remained independently associated with reverse remodeling across multiple models, suggesting that the extent of myocardial fibrosis, rather than the underlying etiology itself, may better reflect the myocardial substrate amenable to reverse remodeling." (PMID 40429491, 2025). "Emerging research has consistently shown that Galectin-3 mediates fibrosis, exemplified by inhibiting Galectin-3 that reduces the inflammatory activation of TLR4 and downstream NF-κB to prevent myocardial fibrosis." (PMID 39407295, 2024). "Thus, reducing Galectin-3 level might be a new therapeutical target to prevent myocardial fibrosis." (PMID 37297827, 2023). "LGALS3 expression and influence of the lncRNA SNHG20 and miR-335 regulatory factors were assessed in the process of myocardial fibrosis and hypertrophy induced by angiotensin II (Ang II) in a murine experimental model." (PMID 35053194, 2021). "This study aimed to assess perindopril and a galectin-3 inhibitor (modified citrus pectin, MCP) for their effects on ventricular remodeling and myocardial fibrosis in rabbits with ischemic heart failure." (PMID 30967790, 2019). "We also demonstrated that galectin-3 and MMP-2 levels increased according to the severity of myocardial fibrosis after adjusting for confounding factors." (PMID 30413105, 2018). "In experimental HF models, MR blockade decreases the expression of galectin-3 (Gal-3) and soluble ST2 (sST2) without interfering with IL-33-mediated cardioprotection, which are associated with the reduction of myocardial fibrosis and inflammation." (PMID 41438090, 2025). "Unfortunately, the role of other biomarkers of myocardial fibrosis such as ST2 or galectin-3 was not well established, and they were not introduced in clinical practice." (PMID 35783848, 2022). "Last, the circulatory galectin-3 levels were not analyzed based on a comparison of their expression in cardiac tissues with histologically proven myocardial fibrosis." (PMID 34722704, 2021). "In the presented follow-up study, changes in galectin-3 values were well correlated with CMR measures of myocardial fibrosis, but not with changes in the overall clinical and functional status of the disease over the 5-year follow-up." (PMID 34830647, 2021). "In experimental studies, it was found that aldosterone, through the activation of macrophages, promotes the production of active substances, including galectin-3, which increases the synthesis of type I and type III collagen by fibroblasts and leads to the development of myocardial fibrosis." (PMID 32784491, 2020). "This is in line with the observation that although levels of galectin measured in myocardial tissue samples correlate well with the degree of myocardial fibrosis the correlation of circulating galectin-3 levels and cardiac fibrosis is not as strong." (PMID 31885743, 2019). "Galectin-3 antagonism with MCP and aldosterone opposition reversed isoproterenol-induced left ventricular systolic dysfunction, thereby preventing the development of myocardial fibrosis in this mice model with selective cardiac hyperaldosteronism." (PMID 31683865, 2019). "Galectin-3 and ST2 are emerging biomarkers involved in myocardial fibrosis." (PMID 29367540, 2017). "Higher galectin-3 levels post-HTx might be related to cardiomyocyte hypertrophy and myocardial fibrosis after HTx but, of note, elevated galectin-3 levels are not related to the time period since HTx." (PMID 27301475, 2016).
atherosclerosis (121 papers, 2013 to 2026). A disease characterized by the build-up of fatty material and calcium deposition in the arterial wall resulting in partial or complete occlusion of the arterial lumen. "LGALS3 encodes Galectin-3, a multifunctional protein involved in atherosclerosis progression through macrophage activation and foam cell formation." (PMID 41544081, 2026). "Genetic galectin-3 deficiency attenuated, and conversely nigericin exacerbated macrophage death, vascular inflammation and atherosclerosis in HFD-fed ApoE-/- mice." (PMID 41795807, 2026). "LGALS3, encoding the atherosclerosis marker galectin-3, was a main driver of this overrepresentation." (PMID 41815328, 2026). "Background and Objectives: Galectin-3 (Gal-3), a pro-inflammatory cytokine, has been implicated in atherosclerosis and adverse cardiovascular outcomes." (PMID 40870433, 2025). "This cluster includes the following keywords: atherosclerosis risk, cardiorenal syndrome, chronic kidney disease, and galectin-3." (PMID 40747108, 2025). "Elevated levels of galectin-3 have been linked to increased inflammation, fibrosis, and the progression of atherosclerosis." (PMID 40430046, 2025). "The involvement of Galectin-3 in atherosclerosis is thought to be linked to its pro-inflammatory and pro-fibrotic properties." (PMID 38170009, 2023). "The expression of atherosclerosis-associated modulation markers Lgals3, Fn1, and Serpine1 (encoding PAI1) was increased at baseline and with 2.5 μg/mL MBD-Chol in the PcntSMC–/– SMCs, but these markers did not increase in the WT SMCs until 10 μg/mL MBD-Chol." (PMID 37937642, 2023). "Galectin-3 plays a pro-inflammatory role in the occurrence and development of atherosclerosis and can be used as a risk factor for atherosclerosis." (PMID 35083706, 2022). "Elevated levels of Galectin-3 are connected to atherosclerosis and to the risk of atherosclerotic plaque formation, as well as destabilization." (PMID 35683362, 2022). "The amplification of cardiovascular system inflammatory condition and accumulation of lipids in macrophages caused by galectin-3 are the most important mechanisms of atherosclerosis development, which are stimulated by local or circulating galectin-3." (PMID 35053194, 2021). "The tests included: inhibition of haemaglutination by galectin-3, reduction of heart inflammatory condition, suppression of organ fibrosis and reduction of atherosclerosis in mice with apolipoprotein E deficiency." (PMID 35053194, 2021). "The association between galectin-3 and atherosclerosis has also been verified by studies in MI patients and patients who received coronary angiography." (PMID 33195327, 2020). "Taken together, these findings indicate that galectin-3 deficiency favors a less fibrotic and more inflammatory plaque phenotype implying a protective role for galectin-3 against the progression of atherosclerosis." (PMID 32295421, 2020). "The authors describe a progressive loss of the SMC contractile profile with atherosclerosis development, together with a gain in the pro-inflammatory gene Lgals3+ (galectin 3), shared with macrophages and associated with disease progression, supporting a transitional SMC state." (PMID 40497946, 2025). "Galectin-3 is implicated in the pathogenesis ofinflammation and atherosclerosis." (PMID 39076571, 2024). "In addition, galectin-3 has been suggested to be implicated in the pathophysiology of atherosclerosis and vascular calcification, presenting potentially prognostic value in patients with myocardial infarction and acute stroke." (PMID 38519721, 2024). "Galectin-3 is a biomarker implicated in atherosclerosis, particularly in coronary arteries." (PMID 36673621, 2023). "Levels of Galectin-3 are associated with the risk of atherosclerosis." (PMID 35683362, 2022).
atherosclerosis (continued). "So, Galectin-3 can be used as a new biomarker for atherosclerosis risk assessment helping to identify diabetic patients who may need an early CAD intervention to reduce the mortality of the cardiovascular disease and increase life expectancy." (PMID 34616230, 2021). "In patients with rheumatoid arthritis, galectin-3 had a markedly positive association with arterial stiffness and atherosclerosis presented as increased PWV, carotid artery intima-media thickness, systemic vascular resistance, pulse pressure, and decreased total arterial compliance." (PMID 34437403, 2021). "Furthermore, one experimental study demonstrated that inhibition of galectin-3 reduces atherosclerosis in apolipoprotein E-deficient mice, suggesting that galectin-3 plays a critical role in the development of atherosclerosis." (PMID 33195327, 2020). "Moreover, galectin-3 deficiency, in a mice model of atherosclerosis (ApoE−/−), decreased plaque size, its necrotic core, and collagen content, which was consistent with our findings." (PMID 33238643, 2020). "Therefore, galectin-3 can be involved in the pathogenesis of ACSs caused by atherosclerosis." (PMID 35053194, 2021). "Additionally, galectin-3 has been implicated in atherosclerosis and may promote insulin resistance, lipolysis, and glucose intolerance." (PMID 32294902, 2020). "Galectin-3 is statistically significantly inversely correlated, albeit weakly, with HDLc, which supports the protective role of HDLc in atherosclerosis." (PMID 40430046, 2025). "Among the most promising candidates in this arena are galectin-3 and pentraxin-3, both of which have garnered significant attention for their roles in inflammation and atherosclerosis—two pivotal processes that underpin the pathophysiology of both CCS and AF." (PMID 40430046, 2025). "Due to its multifunctional properties, Lgals3/galectin-3 plays different roles in several diseases, such as cancer, chronic inflammation, atherosclerosis, and cardiovascular diseases." (PMID 39595213, 2024). "In particular, galectin-3 has been suggested to promote increased arterial stiffness and atherosclerosis through its role in inflammation, cell migration and cell–cell interaction." (PMID 38519721, 2024). "Exogenous act-hMMP9 increased inflammation and initiated atherosclerosis in KK mice at 2 and 10 weeks: increased vessel wall thickness, lipid accumulation, and Galectin-3+ macrophage infiltration into the carotid arteries." (PMID 38660518, 2024). "Galectin-3 is now recognized as both a cardiovascular inflammatory biomarker anda mediator of atherosclerosis." (PMID 39076571, 2024). "Over the past decades, the prognostic role of serum galectin-3 as a biomarker linking oxidative stress, inflammation and fibrosis has been demonstrated in many pathological conditions such as HF, atherosclerosis, CKD and cancer." (PMID 38195853, 2024). "Despite the presence of Lgals3, there are few derivatives of macrophage-like state in advanced atherosclerosis." (PMID 36604627, 2023). "Atherosclerotic plaques express high levels of galectin-3 and correlate with the degree of atherosclerosis and inflammation." (PMID 36873388, 2023). "Plasma galectin-3 levels are increased in patients with coronary artery diseases and atherosclerosis." (PMID 36873388, 2023). "Galectin-3 has a critical role in vascular remodeling and atherosclerosis through a variety of mechanisms." (PMID 37240626, 2023). "In atherosclerosis, a subset of Lgals3- macrophages exhibiting highly expressed Mmp12 accumulated in the advanced plaques with pro-inflammatory characteristics." (PMID 37359523, 2023). "Galectin-3 is an inflammatory mediator that promotes atherosclerosis by affecting multiple key cells with a structural and functional role in the arterial wall, such as ECs, SMCs, and immune system cells." (PMID 36362423, 2022).